IL33 (interleukin 33)
Diseases named in the same sentence as IL33 in open-access papers (continued):
Sharing a sentence is not in itself a finding about the gene and the disease.
metastatic melanoma (2 papers, 2021 to 2023). A melanoma that has spread from its primary site to another anatomic site. "In metastatic melanoma samples, IL-33 is probably derived from stromal cells and may improve prognosis through enhancing anti-tumor immune responses." (PMID 33621202, 2021).
migraine (2 papers, 2024 to 2025). "Previous studies have shown that the interaction between IL-33 and microglia mediates pain sensitivity related to migraines." (PMID 37450927, 2024). "Therefore, abnormal IL-33/ST2 signaling pathway activation can aggravate the central sensitization of migraine and other diseases." (PMID 37450927, 2024).
minimal change disease (2 papers, 2023 to 2024). "Similar anti-inflammatory benefits were observed with the IL-33 treatment of experimental models of minimal change nephropathy." (PMID 38672094, 2024). "Notably, the expression of the IL-33 receptor complex has been confirmed in podocytes and IL-33 expression has been shown to be upregulated in patients with minimal change nephropathy." (PMID 38672094, 2024).
monoclonal gammopathy of undetermined significance (2 papers, 2019 to 2024). "According to our results, IL‐33 expression levels were reduced in monoclonal gammopathy of undetermined significance, MM, and relapsed MM patients, relative to normal contributors (p < 0.05)." (PMID 38737470, 2024). "For instance, our team investigated the plasma concentrations of IL-33 in 44 multiple myeloma (MM) subjects and 13 subjects with monoclonal gammopathy of undetermined significance (MGUS)." (PMID 31652497, 2019). "There are numerous possible pathogenetic and therapeutic implications related to the role of IL-33 in patients with monoclonal gammopathies." (PMID 31652497, 2019).
mucositis (2 papers, 2019 to 2025). Mucositis is inflammation and damage of the mucous membranes lining the mouth and other parts of the gastrointestinal (GI) tract. "IL-33 might exacerbate these diseases through the induction of eosinophils, type 2 innate lymphoid cells, mast cells, the production of pro-inflammatory and pro-fibrotic cytokines, inducing mucositis, or directly promoting the proliferation and metastasis of cancer cells." (PMID 30774633, 2019).
oropharyngeal squamous cell carcinoma (2 papers, 2020 to 2024). "In patients with oropharyngeal squamous cell carcinoma (OPSCC), the expression level of IL-33 had no prognostic value." (PMID 33634017, 2020). "In oropharyngeal squamous cell carcinoma (OPSCC), the role of IL-33 has not yet been determined." (PMID 38662248, 2024).
osteonecrosis of femoral head (2 papers, 2017 to 2022). "We aimed to investigate the potential role of IL-33 in the development of osteonecrosis of femoral head (ONFH)." (PMID 28167850, 2017).
pericarditis (2 papers, 2022 to 2023). An inflammatory process affecting the pericardium. "The pathogenic role of IL-1 family members such as IL-1α, IL-1β, and IL-33 in pericarditis has been studied clinically and preclinically." (PMID 35251049, 2022). "In fact, exogenous short administration of IL-33 seems to be protective in the obesogenic condition in mice, while IL-33 up-regulation in healthy mice could determine pericarditis." (PMID 36768322, 2023). "In addition, we and others have shown that in vivo administration of IL-33 alone can induce acute pericarditis by activating only innate immunity in mice." (PMID 35251049, 2022).
peripheral nerve injury (2 papers, 2017 to 2018). Injury to a peripheral nerve. "For example, IL-33, a member of the IL-1 family of cytokines, expressed in oligodendrocytes within the spinal cord after peripheral nerve injury in mice involves the generation of neuropathic pain behavior, and this pain behavior is attenuated by inhibition of IL-33/ST2 (IL-33 receptor) signaling." (PMID 28951789, 2017). "Therefore, IL-33 upregulation in the spinal cord after peripheral nerve injury may reflect changes in neuron, astrocyte, and oligodendrocytes function." (PMID 29329586, 2018).
placental insufficiency (2 papers, 2018 to 2024). Failure of the placenta to deliver an adequate supply of nutrients and oxygen to the fetus. "Overall, our findings demonstrated that the reduction of IL-33 production was connected with the reduced functional capability of trophoblast cells, thus inducing placental insufficiency that has been linked to the development of PE." (PMID 29736154, 2018).
plaque psoriasis (2 papers, 2020 to 2025). "Interleukin-33 (IL-33) is markedly elevated in lesional skin and serum of patients with moderate-to-severe plaque psoriasis." (PMID 40681996, 2025). "We have confirmed that patients with psoriasis vulgaris have higher levels of alarmin IL-33 than healthy controls (p < 0.01)." (PMID 32377165, 2020).
post-traumatic stress disorder (2 papers, 2023 to 2024). An anxiety disorder precipitated by an experience of intense fear or horror while exposed to a traumatic (especially life-threatening) event. "Elevated levels of IL-33, iNOS, HO-1, and MIP-1β concentrations have been reported in depressed individuals with and without the post-traumatic stress disorder (PTSD)." (PMID 37759873, 2023).
prostate tumors (2 papers, 2016 to 2024). "Given the known favorable role of ILC2s in immune responses, this association suggests a complex interplay involving IL-33, eosinophils, and ILC2s in the context of human prostate tumors." (PMID 38524132, 2024). "To further elucidate the immune landscape functionally linked to the IL-33 expressing environment, we conducted an immunohistochemistry (IHC) study targeting eosinophils in human prostate tumors characterized by high and low IL-33 content." (PMID 38524132, 2024). "This discovery provides the impetus for future therapeutic applications related to IL-33/ILC2 axis in patients with human prostate tumors." (PMID 38524132, 2024). "More studies are required to address the contribution of IL-33/ILC2s/eosinophils alliance to the immune response in various forms and stages of the prostate neoplasms." (PMID 38524132, 2024). "The present human studies conclusively demonstrate that the level of IL-33 gene is downregulated in human metastatic prostate cancer compared to human benign and primary prostate tumours." (PMID 27619158, 2016). "Knowing that high IL-33 content is associated with initial stages of the disease progression and, at the same time, is favorable for ILC2 cell functionality, we performed an IHC study targeting eosinophils in human prostate tumors with high and low IL-33 content." (PMID 38524132, 2024). "Collectively, these results indicate that the expression level of IL-33 may be a potential candidate as the first immune prognostic marker for prostate tumour transition to its metastatic form." (PMID 27619158, 2016). "To evaluate the correlation between IL-33 and MHC/HLA expression (and consequent T cell infiltration) in human tumors, we used RNA-sequencing data collected from resected prostate tumours." (PMID 27619158, 2016).
Psoriasiform dermatitis (2 papers, 2016 to 2017). A skin abnormality characterized by redness and irritation, with thick, red skin that displays flaky, silver-white patches (scales). "To assess whether overexpression of IL-33 in mice keratinocytes worsens the development of IMQ-induced psoriasiform dermatitis, we applied IMQ cream on the right ear of hK14mIL33tg and WT mice for 7 consecutive days." (PMID 28702024, 2017). "In addition, we observed enhanced mRNA expression of the interleukins Il17c, Il23 and Il33 which are key players in human psoriasiform dermatitis." (PMID 27050272, 2016).
psychosis (2 papers, 2018 to 2021). "The positive correlation of IL-33 with positive PANSS symptoms in remission suggests its potential role in underling mechanisms of psychosis onset." (PMID 29988422, 2018). "Considering involvement of Gal-3 and the IL-33/ST2 pathway interactions in the somatic states, this interplay could be also involved in onset, clinical presentation and somatic comorbidity of psychosis." (PMID 29988422, 2018).
pulmonary edema (2 papers, 2019 to 2021). Accumulation of fluid in the lung tissues causing disturbance of the gas exchange that may lead to respiratory failure. "We hypothesized that IL-33 treatment may act through ILC2s to stimulate IL-13 production, leading to acute lung injury, vascular permeability, and resulting pulmonary edema." (PMID 33974563, 2021).
pulmonary sarcoidosis (2 papers, 2020 to 2022). Sarcoidosis affecting the lung parenchyma. "IL-33 exerts pleiotropic roles in regulating inflammatory responses in different disease conditions, such as pulmonary sarcoidosis and spinal cord injury." (PMID 35269441, 2022).
retinopathy of prematurity (2 papers, 2022 to 2023). A bilateral retinopathy characterized by neovascularization, scarring, retinal detachment, and eventually blindness. "Can IL-33 and Endocan be new markers for retinopathy of prematurity?" (PMID 36856242, 2023).
Seizure (2 papers, 2017 to 2025). A seizure is an intermittent abnormality of nervous system physiology characterized by a transient occurrence of signs and/or symptoms due to abnormal excessive or synchronous neuronal activity in the brain. "Seizure can induce sever pathologies including cell death, neuronal loss and inflammatory responses, which can contribute to switching pro-IL-33 to mature IL-33." (PMID 29311813, 2017). "Further, our data showed, for the first time, that CBD treatment regulated immunologic responses to seizures by lowering proinflammatory cytokines (IL-33 and IL-6) production and enhancing the level of IC protein of PD-1 within the CNS as well as systemically in the peripheral blood." (PMID 40177581, 2025).
silicosis (2 papers, 2023 to 2024). Silicosis is a respiratory disease caused by breathing in (inhaling) silica dust. "Patients with silicosis seem to have a chronic inflammatory process that is consistent with the augmented levels of some pro-inflammatory cytokines, i.e., IL-1β, IL-6, IL-7, IL-8, IL-16, IL-17A, IL-33 and TNF-α were observed in this work." (PMID 36675056, 2023).
skin rashes (2 papers, 2021 to 2024). "Based on the significantly higher incidence of skin rashes occurring with MIS-C and the higher levels of cytokines (IL-5, IL-8, IL-13, and IL-33) known to influence eosinophil activity, we performed a further evaluation of eosinophils and ELR." (PMID 38932242, 2024).
skin reaction (2 papers, 2017 to 2018). "During tissue damage, fl IL-33 exacerbated radiation-induced skin reaction." (PMID 28702024, 2017).
spinal cord injuries (2 papers, 2019 to 2022). "Meningeal ILC2s were activated in an IL-33-dependent mechanism after spinal cord injury (SCI), releasing type-2 cytokines and demonstrating that ILC2s proliferate in response to IL-33 activation." (PMID 35224555, 2022).
Thrombocytosis (2 papers, 2022 to 2025). Increased numbers of platelets in the peripheral blood. "Thrombocytosis has positive correlation with IL-33 (r = 0.404; p = 0.004), Gal-1 (r = 0.333; p = 0.024), IL-1 (r = 0.335; p = 0.020) values in serum, respectively." (PMID 35611243, 2022). "Possible explanation for thrombocytosis and positive correlation between higher number of platelets and mediators of interest is that enhanced levels of IL-1 and IL-33 could directly induce megakaryopoiesis and subsequently thrombocytosis." (PMID 35611243, 2022).
Thrombosis (2 papers, 2018 to 2022). "In vitro and in vivo experiments showed that MkL assumed and managed antigenic proteins and pathogens, stimulated CD4+T cell triggering in an MHC II-dependent modality and may have a central role in IL-33-induced thrombosis in COVID 19 patients." (PMID 36498859, 2022).
toxocariasis (2 papers, 2021 to 2025). A parasitic infection caused by worms found in domestic animals. "Our observations indicate that the presence of the IL-33/ST2 pathway induces susceptibility to toxocariasis, which could be a possible therapeutic target for study in the control of larval migration and prevention of tissue damage." (PMID 34324507, 2021). "Studies have indicated that Th2 response is the main immune defense mechanism against toxocariasis, however, there are still few studies related to this response, mainly the IL-33/ST2 pathway." (PMID 34324507, 2021). "IL-33 is an alarmin that binds to the ST2 receptor, and some studies have observed an increase in this cytokine in toxocariasis, however there are no studies regarding the IL-33/ST2 role in this infection." (PMID 34324507, 2021).
tuberculous pleurisy (2 papers, 2014 to 2021). "Researches showed that the level of interleukin-33 (IL-33) in pleural fluid was significantly higher in patients with tuberculous pleurisy than in other causes." (PMID 34425761, 2021). "IL-33 has an important diagnostic value in the diagnosis of tuberculous pleurisy." (PMID 34425761, 2021). "Li and other scholars also showed that the sensitivity of IL-33 in the diagnosis of tuberculous pleurisy was 83.9%, the specificity was 87.3%, and the area under the ROC curve was 0.823." (PMID 34425761, 2021). "Combined IL-33, ADA, TSPOT.TB, the diagnostic specificity was 100%, and the sensitivity was 88.5%, suggesting that the combined detection has a higher diagnostic value for tuberculous pleurisy." (PMID 34425761, 2021). "Therefore, IL-33 may be involved in the pathogenesis and development of tuberculous pleurisy, and its elevated level may play a role in the stimulation of inflammation by mycobacterium tuberculosis." (PMID 34425761, 2021). "Therefore, in tuberculous pleurisy, IL-33 and IFN-γ may form a coupled positive feedback loop." (PMID 34425761, 2021).
viral myocarditis (2 papers, 2018 to 2021). Myocarditis that is caused by an infection with a viral agent. "In a murine model, IL‐33 improved CVB3‐induced viral myocarditis by inducing macrophage polarization to the M2 type." (PMID 33305406, 2021).
abscesses (1 paper, 2022). "Several epithelial crypts with positive IL-33 expression were associated with the presence of intraepithelial inflammatory cells and crypt-abscesses." (PMID 35798804, 2022).
acromegaly (1 paper, 2024). Acromegaly is an acquired disorder related to excessive production of growth hormone (GH) and characterized by progressive somatic disfigurement (mainly involving the face and extremities) and systemic manifestations. "Our previous study on 20 patients with acromegaly showed that IL33 is higher in patients with acromegaly compared to healthy controls." (PMID 38329608, 2024). "Aim of the study was to evaluate Interleukin-33 (IL33) and the skin perfusion of hands in patients with acromegaly (AP) and healthy controls (HC)." (PMID 38329608, 2024). "The same data were obtained in this study on a larger sample of patients, confirming that in patients with acromegaly the inflammation is persistent due to the increase in the proinflammatory IL33, independently of the biochemical control of the disease." (PMID 38329608, 2024).
acute-on-chronic liver failure (1 paper, 2019). Acute-on-chronic liver failure (ACLF) is an extreme condition during the natural history of chronic HBV infection, with a relatively high short-term mortality. "Upregulation of IL-33 and sST2 in serum has been shown to exist in ALF and acute-on-chronic liver failure in patients, correlating with the intensity of necrosis as assessed by transaminase activity." (PMID 31507607, 2019). "In HBV acute-on-chronic liver failure (ACLF), seric IL-33 and ST2s concentrations are pronouncedly higher than the concentrations observed in CHB patients." (PMID 31507607, 2019).
adenovirus infection (1 paper, 2016). "The protective roles of the IL-33/ST2 axis have been reported during chronic viral infection in the liver, via promoting CD8+ T-cell responses, repressing inflammatory cytokine TNF-α, inducing type 2 innate lymphoid cells (ILC2), and protecting the liver in acute adenovirus infection." (PMID 26943125, 2016).
adult-onset Still disease (1 paper, 2022). A rare inflammatory multisystem disorder characterized clinically by fever of unknown origin, arthralgia or arthritis, hyperleucocytosis, and typical skin rash. "The potential efficacy of IL-18 blockade in adult-onset Still disease and of IL-33 blockade in AD are being assessed in clinical trials." (PMID 36012744, 2022).
alcohol (1 paper, 2020). "The production of NO can be stimulated by IL-33, which is highly expressed in patients with ALD and serves as an alarm during severe tissue injury, and is responsible for the formation of hydroxyl radicals that impair mitochondrial respiration during alcohol-induced liver damage." (PMID 32719658, 2020).
amebiasis (1 paper, 2022). A parasitic infectious disorder caused by amoebas. "This IL-33-mediated defense from amebiasis was associated with the induction of type 2 immune responses and while IL-33 did not require T and B cells, the presence of ILC2s was sufficient to confer protection." (PMID 34400793, 2022). "Treatment with recombinant IL-33 protected mice from amebic infection and intestinal tissue damage; moreover, blocking IL-33 signaling made mice more susceptible to amebiasis." (PMID 34400793, 2022). "We first tested if IL-33 was similarly increased in the intestinal tissue upon E. histolytica infection in the mouse model of amebiasis." (PMID 34400793, 2022). "The upregulation of IL-33 transcripts in the human colon during amebic infection was the first indication of a potential role of IL-33 signaling in amebiasis." (PMID 34400793, 2022). "Using a mouse model of amebiasis, we demonstrate here that IL-33 protected from amebic infection and colonic tissue damage." (PMID 34400793, 2022). "As infection increased IL-33 in both humans and in mice, we utilized the mouse model of amebic colitis to investigate if IL-33 protected from amebiasis." (PMID 34400793, 2022). "Together, these data demonstrated that endogenous IL-33 protected from colonic amebiasis." (PMID 34400793, 2022). "In this study, we found that treatment with IL-33 reduced epithelial damage during amebiasis." (PMID 34400793, 2022). "Hence, it was important to determine which cell types are responsible for IL-33-mediated protection from amebiasis." (PMID 34400793, 2022). "IL-33 may act to protect from amebiasis in part by dampening inflammation." (PMID 34400793, 2022).
amebic colitis (1 paper, 2022). "Together these data demonstrated that IL-33 induced a type 2 immune response and diminished inflammations during amebic colitis." (PMID 34400793, 2022). "Endogenous IL-33 signaling and exogenous treatment with recombinant IL-33 protected from amebic colitis." (PMID 34400793, 2022). "Future work should focus on determining the role of mast cells and basophils in IL-33-mediated protection from amebic colitis." (PMID 34400793, 2022). "We sought to determine if IL-33 was acting on Th2 cells or/and ILC2 cells to protect from amebic colitis by inducing a type 2 immune response." (PMID 34400793, 2022). "We observed that IL-33 did not require the presence of T and B cells to confer protection from amebic colitis, however did require ILC2s." (PMID 34400793, 2022). "However, the role of IL-33 and ILC2s in amebic colitis has not previously been studied." (PMID 34400793, 2022).
aortic aneurysm (1 paper, 2020). A ruptured aneurysm located in the wall of the proximal portion of the descending aorta proceeding from the arch of the aorta. "We assessed by quantitative PCR (qPCR) the expression of IL-33, ST2, Th1 and Th2 cytokines within inflammatory aortic lesions of 18 LVV patients who underwent a surgical repair for an aortic aneurysm/dissection." (PMID 32286393, 2020).
aplastic anemia (1 paper, 2015). Anemia resulting from bone marrow failure (aplastic or hypoplastic bone marrow). "In this study, we aim to evaluate the balance of interleukin (IL)-33 and its soluble receptor sST2 in patients with aplastic anemia (AA)." (PMID 26677348, 2015).